CFAP184 (cilia and flagella associated protein 184)
Description:
In complex with CFAP263, acts as a regulator of ciliary beating that connects radial spoke 3 (RS3) to the inner dynein arm (IDA) and the nexin-dynein regulatory complex (N-DRC). The complex is positioned parallel to N-DRC and forms a connection between the arch at the base of RS3, the IDA tail and N-DRC.
Synonyms: CCDC96; FLJ90575
Tractability: Small molecule: a structure with a bound ligand is known. PROTAC: ubiquitination databases record sites on it.
Gene: Protein-coding gene on chromosome 4 (7,040,849 to 7,043,001, reverse strand). Ensembl gene ENSG00000173013.
Subcellular location: Cell projection, cilium; Cytoplasm, cytoskeleton, microtubule organizing center, centrosome
Gene Ontology:
Molecular function: protein binding
Biological process: cilium assembly
Cellular component: axoneme; ciliary basal body; centrosome; cilium
Genetic constraint (gnomAD): Loss-of-function variants: 27 observed, 22.74 expected, observed/expected ratio (o/e) 1.19, 90% interval 0.87 to 1.63. The upper end of that interval is the gene's LOEUF score, 1.63, which puts it in group 6 of 6, group 1 being the genes least tolerant of losing a copy. Missense variants: 795 observed, 645.95 expected, observed/expected ratio (o/e) 1.23, 90% interval 1.16 to 1.3. Synonymous variants: 328 observed, 282.02 expected, observed/expected ratio (o/e) 1.16, 90% interval 1.06 to 1.27.
Homologues: Orthologues: chimpanzee CFAP184 (98% identical).
Diseases named in the same sentence as CFAP184 in open-access papers:
CFAP184 is named in the same sentence as 1 disease in open-access papers, as found by Europe PMC text mining. Sharing a sentence is not in itself a finding about the gene and the disease.
CFAP184 shares sentences with these, for which no sentence is quoted: male infertility (1 paper).